BCAR3 (BCAR3 adaptor protein, NSP family member)
Diseases named in the same sentence as BCAR3 in open-access papers (continued):
Sharing a sentence is not in itself a finding about the gene and the disease.
tumor (continued). "Moreover, it was found that BCAR3 activates the CCND1 promoter and CCND1 is believed to be an important tumor promotor in HNSCC that drives cells through the G1–S checkpoint of the cell cycle and contributes to unscheduled DNA replication." (PMID 34707118, 2021). "In accordance with the in vitro results, the subcutaneous xenografts of SCC25 cells in which BCAR3 was knocked down exhibited reduced growth and decreased tumor weight compared with those of control HNSCC cells, which indicates that interference in BCAR3 expression suppresses HNSCC growth in vivo." (PMID 34707118, 2021). "We found that BCAR3 promoted HNSCC cell proliferation and tumor growth in vivo, which could partially account for the observed decreased survival." (PMID 34707118, 2021). "BCAR3 promotes the proliferation of HNSCC cells in vitro and tumor growth in vivo." (PMID 34707118, 2021). "Moreover, several genes (such as BCAR3, GNAS, ISLR and RASGRP3) exhibited opposite patterns of AS events of a parent gene in tumor and normal tissues." (PMID 31695792, 2019).
BCAR3 also shares sentences with these, for which no sentence is quoted: estrogen resistance (2 papers); bladder carcinoma (1); colorectal cancer (1); endometrial cancer (1); head and neck cancer (1); Insulin resistance (1); lung carcinoma (1); neuroblastoma (1); pancreatic cancer (1); thyroid cancer (1).